RAF1 (Raf-1 proto-oncogene, serine/threonine kinase)
Diseases named in the same sentence as RAF1 in open-access papers (continued):
Sharing a sentence is not in itself a finding about the gene and the disease.
cryptorchidism (2 papers, 2018 to 2024). The failure of one or both testes of a male fetus to descend from the abdomen into the scrotum during the late part of pregnancy. "Nevertheless, 3 subjects who did not experience delayed puberty had offspring: 2 males carrying heterozygous PTPN11 mutations, 1 of them with cryptorchidism, had children by means of assisted reproductive techniques, and 1 female (RAF1 mutation) had a spontaneously conceived pregnancy." (PMID 39897954, 2024).
depression (2 papers, 2020 to 2026). "RAF1 expression, which was severely repressed in depression models, showed substantial recovery with low-dose curcumin and was nearly normalized with high-dose treatment, approaching Sham group levels." (PMID 41438694, 2026). "Dysregulation of this pathway, particularly involving key nodes like BDNF, RAF1, and downstream effectors such as JUN, has been increasingly implicated in the pathophysiology of Major Depressive Disorder." (PMID 41438694, 2026). "Thus, the current evidence also implicates depression, in line with earlier evidence that activators of the Ras superfamily of GTPases, Raf1 and B-Raf, are dysregulated in postmortem brains of suicide cases." (PMID 30626913, 2020). "Specifically, we observed that CUMS-induced depression models exhibited profound molecular dysregulation characterized by significant BDNF suppression, pathological EGFR overexpression, ERK2 downregulation, pro-inflammatory JUN elevation, RAF1 repression, and chronic stress-driven TNF upregulation." (PMID 41438694, 2026).
endothelial dysfunction (2 papers, 2023 to 2024). In vascular diseases, endothelial dysfunction is a systemic pathological state of the endothelium (the inner lining of blood vessels) and can be broadly defined as an imbalance between vasodilating and vasoconstricting substances produced by (or acting on) the endothelium. "The inhibition of the KIT and RAF1 pathways leads to vascular stem cell damage and endothelial dysfunction." (PMID 37692846, 2023).
esophageal cancer (2 papers, 2022 to 2024). A primary or metastatic malignant neoplasm involving the esophagus. "RKTG/PAQR3-mediated inhibition of Raf/MEK/ERK cascade (exemplified by decreased protein expression levels of Raf-1, p-MEK1 and p-ERK1/2) impairs EMT and, consequently, in vitro cell migration and invasion of esophageal cancer cells and laryngeal squamous cell carcinoma cells." (PMID 35805075, 2022).
HCMV infection (2 papers, 2021 to 2025). "The increase in RAF1-S621 phosphorylation and the loss of total RAF1 expression mirrored increases in AMPKa2 protein levels, which have previously been found to be important for HCMV infection." (PMID 39902964, 2025). "A similar replication defect was observed at a low MOI (0.01), highlighting the importance of RAF1 for HCMV infection." (PMID 39902964, 2025). "We find that pharmacological inhibition of RAF1 inhibits HCMV infection, reducing viral DNA accumulation and the production of viral progeny." (PMID 39902964, 2025). "Collectively, these results suggest the possibility of using these pharmacological RAF1 inhibitors to treat clinical HCMV infection." (PMID 39902964, 2025). "Future experiments will be necessary to elucidate how pharmacological targeting of RAF1 mechanistically impacts HCMV infection." (PMID 39902964, 2025). "HCMV infection induced RAF1 phosphorylation at Ser621, a site known to be phosphorylated by AMPK, and this phosphorylation was reversed with Compound C treatment." (PMID 39902964, 2025). "Here, we show that RAF1 plays an important role in HCMV infection and is regulated by AMPK-mediated phosphorylation." (PMID 39902964, 2025). "Given that growth factor signaling has generally been found to be important for HCMV infection, we hypothesize that RAF1 activation supports HCMV infection." (PMID 39902964, 2025). "Here, we explore the phosphorylation of RAF1 and its contributions to HCMV infection." (PMID 39902964, 2025). "Our data indicate that HCMV infection induces AMPK-specific changes in RAF1 protein phosphorylation, including increasing phosphorylation at RAF1-Ser621, a known AMPK phospho-site, which results in increased binding to the 14-3-3 scaffolding protein, an important aspect of RAF1 protein activation." (PMID 39902964, 2025). "We find that RAF1 phosphorylation during HCMV infection is complex." (PMID 39902964, 2025). "Potentially capturing a broader representation of RAF1 post-translational modifications, HCMV infection induced dramatic changes to the isoelectric point of the majority of migrating RAF1 species, collapsing them and shifting them to a more acidic portion of the gradient." (PMID 39902964, 2025). "We found that AMPK-dependent RAF1-Ser621 phosphorylation increases as HCMV infection progresses." (PMID 39902964, 2025). "Given that sorafenib and regorafenib can inhibit other kinases in the RAF1 pathway, including BRAF, we employed other methods to analyze RAF1’s potential contributions to HCMV infection." (PMID 39902964, 2025). "Multiple points in the growth factor signaling pathway are important for HCMV infection, but the relationship between HCMV and RAF1, a component of the mitogen-activated protein kinase (MAPK) cascade, is not well understood." (PMID 39902964, 2025). "Collectively, our data indicate that HCMV infection and AMPK activation modulate RAF1 activity, which is important for viral replication." (PMID 39902964, 2025). "To address this issue, we targeted RAF1 more specifically via shRNA and CRISPR and found that, in both cases, HCMV infection was reduced, albeit to a smaller extent than with pharmacological treatment." (PMID 39902964, 2025). "The AMP-activated protein kinase (AMPK) is a known regulator of RAF1, and AMPK activity is induced by HCMV infection, which is important for productive HCMV replication." (PMID 39902964, 2025). "Reduced expression of either ARAF or BRAF did not inhibit infection, suggesting that RAF1 is the most important RAF kinase for productive HCMV infection in fibroblasts." (PMID 39902964, 2025). "Of note, overexpression of RAF1 throughout infection does not negatively impact the production of viral progeny, suggesting that increased expression of RAF1 at late time points does not impact HCMV infection." (PMID 39902964, 2025).
HCMV infection (continued). "During HCMV infection, RAF1 populations had a significantly higher negative charge relative to RAF1 during mock infection, resulting in a shift toward pH 3.0, consistent with increased phosphorylation." (PMID 39902964, 2025). "Over-expression of RAF1-S621A did not impact HCMV infection; however, firm conclusions about the potential contributions of RAF1-Ser621 phosphorylation to infection are difficult, given that endogenous RAF1 capable of Ser621 phosphorylation was present in these experiments." (PMID 39902964, 2025). "Compound C treatment reduced the 14-3-3:WT-RAF1 ratio during HCMV infection but did not appreciably change the ratio of co-precipitated 14-3-3:RAF1-S621A, which is again consistent with AMPK activity modulating RAF1–14-3-3 association via serine 621 phosphorylation." (PMID 39902964, 2025).
Hyperglycemia (2 papers, 2008 to 2013). An increased concentration of glucose in the blood. "Raf-1 mediated increase in endothelial cell apoptosis in hyperglycemia is via activation of NF-kB." (PMID 23675062, 2008).
hypopharyngeal carcinoma (2 papers, 2022 to 2023). Carcinoma, predominantly squamous cell, arising from the epithelial cells of the hypopharynx. "Kaplan–Meier & log-rank test and COX’s analysis indicated that RAF1 positive expression and lymphatic metastasis are both independent prognostic risk factors for hypopharyngeal carcinoma." (PMID 35668458, 2022). "Fortunately, in our previous studies, RAF1 has been identified as an independent prognostic risk factor for lymphatic metastasis of hypopharyngeal cancer by transcriptomic sequencing combined with clinical data." (PMID 35668458, 2022). "A previous study had indicated that RAF1 promotes lymphatic metastasis of hypopharyngeal carcinoma by regulating the activity of LAGE1 gene." (PMID 37910477, 2023). "Results showed that in 10 pairs of hypopharyngeal carcinoma primary tumor tissues, the mRNA levels of RAF1 were significantly up-regulated in lymphatic metastasis group compared to non-lymphatic metastasis group." (PMID 35668458, 2022). "In summary, this study verified for the first time that RAF1 can promote lymphatic metastasis of hypopharyngeal carcinoma by regulating LAGE1." (PMID 35668458, 2022). "Through transcriptomic sequencing and bioinformatics analysis of clinical specimens, as well as QRT-PCR and WB assay, RAF1 was proved to be a significantly differential gene between patients with and without lymphatic metastasis of hypopharyngeal carcinoma." (PMID 35668458, 2022).
ischemia (2 papers, 2015 to 2019). A hypoperfusion of the BLOOD through an organ or tissue caused by a PATHOLOGIC CONSTRICTION or obstruction of its BLOOD VESSELS, or an absence of BLOOD CIRCULATION. "Western blot shows that binding of p-AKT to Raf-1 was stimulated by ischemia." (PMID 26442853, 2015). "During ischemia, Akt reduces Raf/MAPK/ERK1/2 activity through phosphorylation of Raf-1." (PMID 31379957, 2019).
lung squamous cell carcinoma (2 papers, 2015 to 2023). "For example, USP1 deubiquitinates FANCD2/FANCI or PCNA to prevent the recruitment of interstrand crosslink repair proteins and translesion DNA polymerase to inhibit DNA repair; USP7 regulates lung squamous cell carcinoma cell proliferation through MEK/ERK signaling by deubiquitinates the Raf-1." (PMID 37107644, 2023).
Mitral regurgitation (2 papers, 2022 to 2024). An abnormality of the mitral valve characterized by insufficiency or incompetence of the mitral valve resulting in retrograde leaking of blood through the mitral valve upon ventricular contraction. "Case 8, with a RAF1 mutation, showed severe obstructive HCM and mitral regurgitation, then underwent Morrow and mitral valvuloplasty procedures." (PMID 35770001, 2022). "Our study found that six patients had RAF1 mutations, and the cardiac abnormalities included not only HCM (obstructive or non-obstructive), but also ASD and mitral regurgitation." (PMID 35770001, 2022).
myxofibrosarcoma (2 papers, 2025). A malignant fibroblastic neoplasm arising from the soft tissue. "A case report of a patient with advanced chemotherapy-refractory myxofibrosarcoma harboring RAF1 S259P mutation and CDKN2A/B loss showed complete radiological response on treatment with MEK inhibitor Trametinib and CDK4/6 inhibitor Palbocilib." (PMID 40556788, 2025). "A recent unique case report described clinical improvement in a patient with myxofibrosarcoma harboring a RAF1 S259P mutation and CDKN2A/Bloss who was treated with a combination of the MEK inhibitor trametinib and the CDK4/6 inhibitor palbociclib." (PMID 41200607, 2025).
Obesity (2 papers, 2022 to 2025). Accumulation of substantial excess body fat. "Second, they identify RAF1 as a potential therapeutic target for combating obesity and metabolic disorders." (PMID 40432214, 2025). "In this study, we found that the expression of RAF1 was significantly increased in hypothalamic AgRP neurons of diet-induced obesity (DIO) mice." (PMID 40432214, 2025). "Under normal chow diet feeding, overexpression of Raf1 in AgRP neurons led to obesity in mice characterized by increased body weight, fat mass, and impaired glucose tolerance." (PMID 40432214, 2025). "Overall, these findings indicate that elevated expression of Raf1 in AgRP neurons in HFD-fed mice results in a mild increase in obesity and related metabolic disorders." (PMID 40432214, 2025). "Conversely, Raf1 knockout in AgRP neurons protected against diet-induced obesity, reducing fat mass and improving glucose tolerance." (PMID 40432214, 2025). "Consequently, Raf1 within AgRP neurons appears to regulate food intake and obesity by enhancing the expression of Agrp and Npy through CREB phosphorylation." (PMID 40432214, 2025). "Collectively, these findings underscore the important role of RAF1 in AgRP neurons in maintaining energy homeostasis and obesity pathogenesis, positioning it and its downstream pathways as potential therapeutic targets for innovative strategies to combat obesity and related metabolic diseases." (PMID 40432214, 2025). "To do so, we first examined the expression of Raf1 in AgRP and POMC neurons of diet-induced obesity (DIO) mice." (PMID 40432214, 2025). "While our work identifies Raf1 as a novel component in this network, the non-unique phenotype highlights that AgRP neurons may exhibit limited redundancy in maintaining pro-obesity functions." (PMID 40432214, 2025).
oral cancer (2 papers, 2015 to 2018). "As a downstream of effector of Raf-1/MEK/ERK, RSK inhibition induced autophagy in oral cancer cells, whereas the ERK inhibitor PD098059 suppressed the autophagic process." (PMID 29970115, 2018). "For example, the gene RAF1 has a medium degree of 10 and the highest connecting score of 8, implying that RAF1 is important for oral cancer development although it is not a hub gene." (PMID 26064958, 2015).
oral squamous cell carcinoma (2 papers, 2022 to 2025). "For example, in oral squamous cell carcinoma (OSCC), circ_CDR1as can act as a sponge for miR-7, leading to the attenuation of the miR-7 targets RAF-1 and PIK3CD, which promotes metastatic progression of tumors by regulating the MAPK/AKT signaling pathway." (PMID 40657383, 2025).
pancreatic acinar cell carcinoma (2 papers, 2023). An adenocarcinoma arising from the pancreas. "Multiple gene fusions involving RAF1 have been implicated in the pathogenesis of solid organ tumors including pancreatic acinar cell carcinomas, and it has been suggested that these fusions are associated with advanced pathologic features." (PMID 37036756, 2023).
Parkinson disease (2 papers, 2015 to 2024). A progressive degenerative disorder of the central nervous system characterized by loss of dopamine producing neurons in the substantia nigra and the presence of Lewy bodies in the substantia nigra and locus coeruleus. "Benserazide, an FDA‐approved Pkm2 inhibitor that inhibits peripheral dopa decarboxylase for the treatment of Parkinson's disease, has a weak effect on the induction of apoptosis; however, our results show that benserazide is still involved in combination therapy with Raf1." (PMID 39073026, 2024).
rectal cancer (2 papers, 2014 to 2023). A primary or metastatic malignant neoplasm that affects the rectum. "Seven genes (IL2RA, IL8RA, IL8RB, IRF2, RAF1, RUNX3, and SEPX1) were significantly associated with rectal cancer (PARTP<0.05)." (PMID 25541970, 2014).
Soft tissue tumors (2 papers, 2022 to 2026). "Based on the clinicopathologic and genomic features of the two cases, RAF 1 fusion-positive soft tissue tumor with S100 and CD34 co-expression was the final diagnosis." (PMID 36229858, 2022). "Recently, a series of low to intermediate grades of soft tissue tumors showing recurrent fusions involving RAF1, BRAF, and NTRK1/2 genes have been defined as a new entity with S100 and CD34 co-expression (without SOX-10 positivity)." (PMID 36229858, 2022).
type 2 diabetes (2 papers, 2021 to 2023). "The non-CHD indications of clinically used drugs included dyslipidemias (PPARA), type 2 diabetes (PPARG and NDUFA13), autoimmune diseases (TNF), neoplasms (RAF1 and PSMA5), circulatory disorders (ABCA1, PLG, ITGB3, and F2), and alcohol-dependency (ALDH2)." (PMID 34675202, 2021).
uveal melanoma (2 papers, 2003 to 2023). A melanoma derived from melanocytes of the uveal tract. "If the RAS/RAF pathway is activated in uveal melanoma, then it is unlikely to be because of activating mutations in RAS or B-RAF, but other members of this pathway have yet to be studied, including A-RAF, C-RAF (RAF1), and GAP1." (PMID 12778069, 2003).
acinar cell carcinoma (1 paper, 2024).
acral melanoma (1 paper, 2024). "Notably, LRRFIP2 has also been involved in fusions with RAF1 in acral melanoma and with MLH1 in hereditary non-polyposis colorectal cancer." (PMID 39906487, 2024).
acute kidney injury (1 paper, 2024). Sudden and sustained deterioration of the kidney function characterized by decreased glomerular filtration rate, increased serum creatinine or oliguria. "Reportedly, Targeting EZH2 protects against acute kidney injury via Raf-1/ERK1/2 pathway." (PMID 39308866, 2024).
acute promyelocytic leukemia (1 paper, 2017). An aggressive form of acute myeloid leukemia (AML), characterized by arrest of leukocyte differentiation at the promyelocyte stage, due to a specific chromosomal translocation t(15;17) in myeloid cells. "Differentiation of NB4 cells, a maturation inducible cell line isolated from human acute promyelocytic leukemia, requires RAF1/MEK/ERK signaling involved in ATRA-induced differentiation in APL cells through enhancing the protein level of C/EBPβ, C/EBPε and PU.1." (PMID 28230720, 2017).
airway hyperresponsiveness (1 paper, 2008). "Inhibition of Raf-1 activity and airway inflammation suppresses smoking-associated airway hyperresponsiveness." (PMID 18976506, 2008). "The present study demonstrates that inhibition of Raf-1-mediated inflammatory signaling may provide a new option for treatment of smoking-associated airway hyperresponsiveness." (PMID 18976506, 2008).
allergic asthma (1 paper, 2024). A asthma with a basis in a pathological type I hypersensitivity reaction. "The current results suggested that CASP3, CCND1, ICAM1, RAF1, and ERBB2 expression are causally related to the risk of allergic asthma." (PMID 39769348, 2024). "The present MR results suggested the presence of associations between the risk of allergic asthma and BAX, CASP3, CCND1, ICAM1, PEBP1, RAF1, and ERBB2 expression." (PMID 39769348, 2024). "Based on the inverse variance weighted method, the MR analysis provided evidence of associations between allergic asthma and BAX, CASP3, CCND1, ERBB2, ICAM1, PEBP1, and RAF1 in the blood." (PMID 39769348, 2024).
bleeding disorders (1 paper, 2021). "Considering that bleeding disorders have been described in patients with mutations in both these genes, the absence of LZTR1 and RAF1 mutations in our patients is very likely related to the limited size of the study cohort rather than to specific genotype–phenotype correlations." (PMID 34857025, 2021).
carcinoid (1 paper, 2012). "Activation of the Raf-1/MEK/ERK-1/2-pathway by leflunomide and teriflunomide can inhibit proliferation and growth of BON carcinoid cells in vitro and in vivo and also decrease expression of neuroendocrine markers in both BON and H727 carcinoid cells." (PMID 22269186, 2012).
chordoma (1 paper, 2013). Chordomas are rare malignant tumors arising from embryonic remnants of the notochord in axial skeleton. "Copy number gains/losses present in more than ≥50% of patients of well-known cancer associated genes for example CDKN2A, CDKN2B, RAF1 and PTEN were found and may play an important role in chordoma development." (PMID 23533570, 2013).
chronic pancreatitis (1 paper, 2020). A chronic inflammatory process causing damage and fibrosis of the pancreatic parenchyma. "A dual inhibitor of sEH and RAF1 proto-oncogene serine/threonine kinase (c-RAF), t-CUPM, significantly inhibited chronic pancreatitis and reduced pancreatic intraepithelial neoplasms (PanIN)." (PMID 33255197, 2020).